SRSF9 (serine and arginine rich splicing factor 9)
Description:
Plays a role in constitutive splicing and can modulate the selection of alternative splice sites. Represses the splicing of MAPT/Tau exon 10.
Synonyms: SFRS9; SRP30C
Tractability: PROTAC: UniProt records ubiquitination sites on it; ubiquitination databases record sites on it; its protein half-life has been measured.
Gene: Protein-coding gene on chromosome 12 (120,456,138 to 120,495,946, reverse strand). Ensembl gene ENSG00000111786.
Subcellular location: Nucleus
Subcellular location (Human Protein Atlas): Nucleoplasm; Nucleoli
Pathways (Reactome):
Metabolism of RNA: Processing of Capped Intron-Containing Pre-mRNA; Transport of Mature mRNA derived from an Intron-Containing Transcript; mRNA 3'-end processing; mRNA Polyadenylation; mRNA Splicing - Major Pathway
Disease: Dengue Virus-Host Interactions
Gene Ontology:
Molecular function: protein binding; protein domain specific binding; RNA binding; nucleic acid binding
Biological process: negative regulation of mRNA splicing, via spliceosome; mRNA processing; mRNA splice site recognition; regulation of alternative mRNA splicing, via spliceosome
Cellular component: nucleoplasm; nucleus
Genetic constraint (gnomAD): Loss-of-function variants: 3 observed, 23.67 expected, observed/expected ratio (o/e) 0.13, 90% interval 0.057 to 0.33. The upper end of that interval is the gene's LOEUF score, 0.33, which puts it in group 1 of 6, group 1 being the genes least tolerant of losing a copy. Missense variants: 161 observed, 294.3 expected, observed/expected ratio (o/e) 0.55, 90% interval 0.48 to 0.62. Synonymous variants: 114 observed, 112.65 expected, observed/expected ratio (o/e) 1.01, 90% interval 0.87 to 1.18.
Homologues: Orthologues: chimpanzee SRSF9 (100% identical), macaque SRSF9 (100% identical), pig SRSF9 (99% identical), dog SRSF9 (99% identical), guinea pig SRSF9 (99% identical), rabbit SRSF9 (99% identical), mouse Srsf9 (98% identical), tropical clawed frog srsf9 (77% identical), rat Srsf9 (76% identical), zebrafish srsf9 (69% identical). Paralogues in human: SRSF1 (73% identical), SRSF6 (41% identical), SRSF4 (41% identical), SRSF5 (36% identical), SRSF7 (33% identical), SRSF3 (29% identical), RSRC2 (18% identical), RSRP1 (17% identical).
Diseases named in the same sentence as SRSF9 in open-access papers:
SRSF9 is named in the same sentence as 37 diseases in open-access papers, as found by Europe PMC text mining. Sharing a sentence is not in itself a finding about the gene and the disease. The quoted sentences say what the papers report.
bladder cancer (11 papers, 2013 to 2024). "More recently, SRSF9 was implicated in the proliferation of a bladder cancer cell line via an unknown mechanism." (PMID 23592547, 2013). "A specific instance of this can be observed in bladder cancer, where miRNA-1 inhibits the function of the serine/arginine-rich splicing factor 9 (SRSF9/SRp30c)." (PMID 38331804, 2024). "In the previous study, tumor suppressive miR-1 induces apoptosis through inhibition of SRSF9 directly in bladder cancer." (PMID 35069733, 2022). "For example, silencing SRSF9 in bladder cancer cells and neuroblastoma cells reduces cell proliferation Subcutaneous tumor growth in mice is promoted by injecting NIH3T3 fibroblasts cells stably expressing SRSF9." (PMID 34445242, 2021). "For instance, the tumor suppressor miR-1 induces apoptosis of bladder cancer cells inhibiting the splicing factor serine/arginine-rich 9 (SRSF9/SRp30c)." (PMID 30453495, 2018). "Interestingly, patients with higher SRSF9 expression tended to have better outcomes after immunotherapy for bladder cancer." (PMID 39132499, 2024). "Another study demonstrated that SRSF9 is upregulated in several cancers, including bladder cancer." (PMID 39132499, 2024). "Although SRSF9 has been recognized as an unfavorable factor in several cancers like bladder cancer, cervical cancer, and colorectal cancer, the molecular function and clear mechanism of SRSF9 in tumorigenesis and proliferation of majority cancers have still been uncovered." (PMID 35069733, 2022). "Moreover, in two human bladder cancer cell lines, Srsf9 downregulation by miR-1 overexpression resulted in significant reduction in cell proliferation, migration, and invasion." (PMID 31791406, 2019). "In cervical and bladder cancers, SFRS9 (Serine and arginine-rich splicing factor 9) has been identified as a protooncogene." (PMID 37025659, 2023). "These clinical data suggest SRSF9 as a proto-oncogene in CRC, similar to its role in glioblastoma, squamous cell lung carcinoma, malignant melanoma and bladder cancer." (PMID 35509101, 2022). "Serine and arginine rich splicing factor 9 (SFRS9) is frequently described as a proto-oncogene in cervical and bladder cancer." (PMID 34336668, 2021). "Specifically, SRSF9 and SND1 have been found overexpressed in several tumor pathologies, such as breast cancer, bladder cancer, glioblastoma, melanoma, or hepatocellular carcinoma, where they have been associated with an increase in cell proliferation, invasion and poor prognosis." (PMID 31561558, 2019).
colorectal cancer (8 papers, 2018 to 2024). A primary or metastatic malignant neoplasm that affects the colon or rectum. "SRSF9 has also been found to function as an m6A-binding protein in colorectal cancer (CRC), enhancing the stability of specific mRNAs involved in CRC malignant progression." (PMID 38842611, 2024). "Whether SRSF9 plays an essential role in colorectal cancer (CRC) progression and can serve as a therapeutic target is largely unknown." (PMID 35509101, 2022). "Also, the overexpression of SRSF9 partly abolished the ferroptosis induced by erastin and tumor growth inhibition in colorectal cancer." (PMID 35069733, 2022).
cervical carcinoma (6 papers, 2020 to 2025). A carcinoma arising from either the exocervical squamous epithelium or the endocervical glandular epithelium. "MicroRNA-802 and miR-1 inhibited cervical cancer proliferation and induced apoptosis by targeting SRSF9." (PMID 40129567, 2025). "It is reported that the downregulation of SRSF9 will inhibit cell proliferation in cervical cancer cells." (PMID 35069733, 2022). "Upon transfection of miR-802 in cervical cancer cells, SRSF9 expression was inhibited, leading to inhibited cell proliferation, cell cycle arrest, and apoptosis." (PMID 34769047, 2021). "SRSF9 was reported to be involved in the cell proliferation and apoptosis in bladder and cervical cancer, and related to prognostic alternative splicing events of renal clear cell carcinoma." (PMID 32883226, 2020). "The SRSF9 is overexpressed in cervical carcinoma, due to the down regulation of miRNA-802 that in normal epithelium binds the 3′-UTR region of SRSF9 transcript inhibiting translation, and causes increase in cell proliferation." (PMID 32596243, 2020). "Besides, another tumor suppressor miR-802 has been demonstrated that miR-802 targets the 3′-untranslated region of SRSF9 directly and suppresses SRSF9 expression, thus inhibiting cell proliferation and inducing apoptosis in cervical cancer." (PMID 35069733, 2022). "In cervical cancer cells, miR-802, which targets the 3′UTR of SRSF9, was found to be downregulated while SRSF9 was upregulated." (PMID 34769047, 2021).
ovarian carcinoma (6 papers, 2010 to 2025). A malignant neoplasm originating from the surface ovarian epithelium. "Upon administration of cisplatin, PANDAR is transferred via exosomes, which aids ovarian cancer cells in rapidly adapting to cisplatin-induced stress through the accumulation of the serine and arginine-rich splicing factor 9 (SRSF9)." (PMID 40757000, 2025). "Elevated levels of SRSF9 are associated with a negative prognosis in ovarian cancer, as SRSF9 promotes an increased transcriptional ratio of sirtuin 4 (SIRT4)/SIRT6." (PMID 40757000, 2025). "Their studies showed that exosomes from ovarian cancer cell lines carrying PANDAR increased the SIRT4/SIRT6 mRNA proportion in ovarian cancer cells by interacting with the target gene SRSF9, significantly enhancing tumor cell survival and chemotherapy resistance in vitro." (PMID 39334866, 2024). "The identification of this positive feedback loop involving SRSF9, USP22, and ZEB1 offers new insights into the molecular mechanisms driving ovarian cancer progression." (PMID 39530604, 2024). "For example, LARP1, an RNA binding protein in ovarian cancer, is a post-transcriptional regulator of survival and tumorigenesis; RNA binding proteins SRSF1 and SRSF9 can promote Wnt signaling-mediated tumorigenesis by enhancing β-catenin biosynthesis." (PMID 32219019, 2020).
breast carcinoma (5 papers, 2019 to 2024). "A comprehensive analysis of SRSF9 mRNA levels in TCGA database identified significant upregulation of SRSF9 in various cancers, notably in GBM, breast cancer, and lung squamous cell carcinoma, with tumor tissues exhibiting markedly higher levels than adjacent normal tissues." (PMID 38842611, 2024). "Cassette exons differentially spliced between high- and low-metastatic breast cancer cells showed enrichment for a number of RNA motifs, which could represent binding sites for RBPs involved in breast cancer malignancy, including PTBP1, SRSF1, and SRSF9." (PMID 33918758, 2021). "Importantly, we found that several RBPs, which are able to recognize the enriched sequences at 5′ and 3′ splice-sites and inside the AS cassette exons, were differentially expressed in breast cancer and during breast tumor progression, including PTBP1, SRSF1, and SRSF9." (PMID 33918758, 2021). "Additionally, among splicing regulators frequently altered in breast cancers (in >5% of tumors), we found different members of SR protein family (such as SRSF1, SRSF2, SRSF3, SRSF4, SRSF6, SRSF9, SRSF10, SRSF11) with at least one predicted binding motif in the CD44 v10 region." (PMID 33143085, 2020).
glioblastoma (5 papers, 2013 to 2024). The most malignant astrocytic tumor (WHO grade IV). "The results indicated that SRSF9 expression levels, in comparison with corresponding normal tissue, were elevated with high frequency in multiple types of cancer samples including glioblastoma (18/20), colon adenocarcinoma (18/20), squamous cell lung carcinoma (19/20) and malignant melanoma (15/20)." (PMID 23592547, 2013).
hepatocellular carcinoma (5 papers, 2019 to 2025). A malignant tumor that arises from hepatocytes. "RBM45 downregulation suppresses hepatocellular carcinoma proliferation, while SRSF9 stabilizes oncogenic transcripts like DSN1, which correlates with lymph node metastasis and an advanced stage of CRC." (PMID 40724932, 2025). "Serine and arginine-rich splicing factor 9 (SRSF9) has been linked to the occurrence and progression of various cancers; however, its effects and mechanism of action hepatocellular carcinoma (HCC) have not been reported." (PMID 35971121, 2022).
cardiac hypertrophy (3 papers, 2024 to 2025). "To corroborate our in vitro results, we performed an in vivo loss‐of‐function study to explore the role of SRSF9 in cardiac hypertrophy." (PMID 38810124, 2024). "To uncover the mechanism underlying SRSF9‐mediated cardiac hypertrophy, we predicted the genes that may bind to SRSF9 based on three databases: ENCORI, catRAPID, and KnockTF2.0." (PMID 38810124, 2024). "Cardiac hypertrophy was also observed in SRSF9‐overexpressing mice as displayed by a marked increase in LVPW;d, HW/TL, and CSA." (PMID 38810124, 2024). "Mechanically, Mettl1 increases SRSF9 expression by inducing m7G modification of SRSF9 mRNA, facilitating alternative splicing and stabilization of NFATc4, thereby promoting cardiac hypertrophy." (PMID 38810124, 2024). "Based on these findings, the present study proposes a novel mechanistic paradigm of cardiac hypertrophy under pressure overload: TAC → Mettl1↑ → SRSF9 mRNA m7G↑ → SRSF9↑ → NFATc4↑ → hypertrophic genes↑ → cardiac hypertrophy/remodeling↑ → cardiac function↓." (PMID 38810124, 2024). "This study reveals that METTL1 plays an important role in driving cardiac hypertrophy by regulating the SRSF9/NFATc4 axis, suggesting that targeting METTL1 could be an efficient way to treat cardiac hypertrophy and HF." (PMID 39979979, 2025). "Furthermore, cardiac hypertrophy, as displayed by the increased CSA and hypertrophic gene expression caused by overexpression of Mettl1, was attenuated by silencing of SRSF9." (PMID 38810124, 2024). "Second, in addition to SRSF9, we cannot exclude the possibility that other mRNAs or tRNAs may also serve as the potential targets of Mettl1 and contribute to cardiac hypertrophy." (PMID 38810124, 2024). "Next, we investigated whether Mettl1‐induced cardiac hypertrophy is mediated by SRSF9." (PMID 38810124, 2024). "We demonstrate that Mettl1 enhances the stability of SRSF9 through m7G modification, leading to upregulation of NFACT4 expression and promotion of cardiac hypertrophy and heart failure progression." (PMID 38810124, 2024). "Supporting this notion, our data demonstrate that SRSF9 acts as a pro‐hypertrophy protein, and knockdown of SRSF9 rescues TAC or Mettl1‐induced cardiac hypertrophy and remodeling." (PMID 38810124, 2024). "The findings indicate that Mettl1 enhances the stability of SRSF9 through m7G modification, resulting in the upregulation of NFACT4 expression and the promotion of cardiac hypertrophy and heart failure progression." (PMID 38810124, 2024).
colon cancer (3 papers, 2013 to 2023). "The same study also showed that the depletion of SRSF9 proteins could inhibit colon cancer cell proliferation." (PMID 32024818, 2020). "Importantly, the β-catenin accumulation induced by either Wnt ligand stimulation or mutation of APC/β-catenin in colon cancer cells is dependent on SRSF1 and SRSF9." (PMID 23592547, 2013). "To directly demonstrate that SR proteins participated in β-catenin synthesis, we knocked-down SRSF1 or SRSF9 in RKO cells, a human colon cancer cell line in which Wnt signalling is relatively low." (PMID 23592547, 2013).
heart failure (2 papers, 2024 to 2025). Inability of the heart to pump blood at an adequate rate to meet tissue metabolic requirements. "Similarly, in heart failure, the upregulation of METTL1 increases m7G modification of SRSF9 mRNA, thereby enhancing its stability and protein expression." (PMID 40698864, 2025). "Elevated SRSF9 levels promote the alternative splicing of NFATc4 pre-mRNA and the activation of hypertrophic gene expression, thereby activating the NFAT signaling pathway, leading to cardiac hypertrophy and remodeling, and ultimately promoting the occurrence and development of heart failure." (PMID 40698864, 2025).
prostate carcinoma (2 papers, 2019 to 2025). A carcinoma that arises from epithelial cells of the prostate gland. "Interestingly, Srsf9 depletion reduces viability of prostate cancer cells." (PMID 31791406, 2019).
amyotrophic lateral sclerosis (1 paper, 2022). Amyotrophic lateral sclerosis (ALS) is a neurodegenerative disease characterized by progressive muscular paralysis reflecting degeneration of motor neurons in the primary motor cortex, corticospinal tracts, brainstem and spinal cord. "In LGG, olfactory transduction was enriched in high expression of SRSF9 and amyotrophic lateral sclerosis ALS, calcium signaling pathway, cardiac muscle contraction, and long-term potentiation were enriched in low expression of SRSF9." (PMID 35069733, 2022).
autism (1 paper, 2025). Persistent deficits in social interaction and communication and interaction as well as a markedly restricted repertoire of activity and interest as well as repetitive patterns of behavior. "In our previous study, we predicted aberrant splicing of the GRIK2 gene due the presence of an ASD-SV SNP near a known binding site for SRSF9, and subsequently confirmed the prediction using RNA-seq data from post-mortem brain tissue from individuals with autism." (PMID 40612695, 2025). "A hypothesis consistent with our results is that individuals with autism should carry SVs in binding sites for SRSF9 and therefore dysregulation of SRSF9-ADAR2-directed RNA-editing, which is supported by reports of decreased editing in post-mortem brain tissue in those with ASD compared to controls." (PMID 40612695, 2025).
cervix (1 paper, 2016). "We have identified and validated CHCHD1, SRSF9 and TMBIM6 as reference genes for studying hypoxia-related gene expression in fresh-frozen clinical samples from squamous cell carcinoma of the uterine cervix by RT-qPCR." (PMID 27244197, 2016).
dilatation (1 paper, 2024). "Echocardiographic analysis showed that the knockdown of SRSF9 significantly alleviated cardiac dysfunction, reduced cardiac dilatation, and LVPW;d induced by TAC." (PMID 38810124, 2024).
glioma (1 paper, 2024). A benign or malignant brain and spinal cord tumor that arises from glial cells (astrocytes, oligodendrocytes, ependymal cells). "Subsequently, we demonstrated that SRSF9 significantly enhanced the proliferation and migration of glioma cells through both gain-of-function and loss-of-function strategies." (PMID 38842611, 2024). "The results showed that higher SRSF9 expression was consistently correlated to shortened overall survival of glioma patients, which was further validated by 6 GEO cohorts for GBM patients." (PMID 38842611, 2024). "Therefore, SRSF9 is pivotal in glioma development and could be a prognostic marker to predict patients’ survival." (PMID 38842611, 2024). "Bioinformatics analysis was performed to explore differential expression of SRSF9 in GBM and its prognostic relevance to glioma patients." (PMID 38842611, 2024). "Firstly, we observed the upregulation of SRSF9 expression in GBM tissues comparing to their adjacent normal controls and found that elevated SRSF9 expression correlates with glioma progression and poor patient prognosis." (PMID 38842611, 2024). "The elevated SRSF9 expression correlates to GBM stages and poor survival of glioma patients." (PMID 38842611, 2024).
lung carcinoma (1 paper, 2022). "Reduced availability of the SRSF1 protein, which regulates autophagy activation, as well as SRSF7 and SRSF9, which induce apoptosis in colon and lung cancer cells by controlling apoptosis." (PMID 36066672, 2022). "Reduced cytoplasmic availability of the Strubbelig-receptor family protein group (SRSF1, SRSF7, SRSF9) can determine autophagy suppression regulated by SRSF1 and apoptosis of colon and lung cancer cells induced by SRSF7 and SRSF9 reduction." (PMID 36066672, 2022).
lymph node metastasis (1 paper, 2022). "Overexpression of SRSF9 was associated with lymph node metastasis and Dukes stage in CRC." (PMID 35509101, 2022). "Overexpression of SRSF9 was positively associated with lymph node metastasis and Dukes stage." (PMID 35509101, 2022). "In the present study, our data reveled that SRSF9 was frequently upregulated in CRC cells as well as in clinical CRC tissue samples, and its overexpression was significantly associated with lymph node metastasis, tumor progression and poor prognosis of patients with CRC." (PMID 35509101, 2022).
squamous cervical cancer (1 paper, 2016). "Thus, CHCHD1, SRSF9 and TMBIM6 seem to be suitable reference genes for studying hypoxia-related gene expression in squamous cervical cancer samples by RT-qPCR." (PMID 27244197, 2016).